VCP (valosin containing protein)
Diseases named in the same sentence as VCP in open-access papers (continued):
Sharing a sentence is not in itself a finding about the gene and the disease.
proteinopathies (continued). "Other familial ALS mutation phenotypes, such as valosin-containing protein (VCP), TAR DNA-binding protein 43 (TDP-43), and superoxide dismutase (SOD1), have been recapitulated in iPSCs showing characteristic proteinopathies, and endoplasmic reticulum (ER) and oxidative stress." (PMID 29479303, 2018). "In addition to sporadic forms, several mutations in different genes, including the C9orf72 (most frequent), granulin (GRN), valosin-containing protein (VCP), TARDBP, SQSTM1 (sequestome), DCTN1 (dynactin), and OPTN (optineurin) have been reported to be associated with TDP-43 proteinopathy." (PMID 26848654, 2016). "In our results, ASO treatment led to a reduction in TDP‐43 pathology, which was accompanied by improved behavioural outcomes in VCP A232E mice, highlighting the therapeutic potential of reducing TDP‐43 dysregulation in multisystem proteinopathy." (PMID 41355735, 2025). "Given that VCP forms a functional hexamer for various protein quality control and vesicular-damage response function, it is not surprising that a single mutant-VCP monomer may compromise the function of the hexamer leading to progressive proteinopathy and associated diseases." (PMID 31358864, 2019). "Multisystem proteinopathy is a complex phenotype that includes FTD, Pagetdisease of the bone, inclusion body myopathy and MND, and can be due tomutations in VCP (valosing containing protein) and otherrecently identified genes." (PMID 29213965, 2015). "VCP and its adaptor FAF2 were recently found to mediate the extraction of G3BP1 from stress granules induced by heat stress, leading to their disassembly, which establishes an interesting connection between stress granule dynamics and the pathogenesis of proteinopathies." (PMID 35164882, 2022).
colorectal cancer (23 papers, 2008 to 2025). A primary or metastatic malignant neoplasm that affects the colon or rectum. "It has been also reported that the level of VCP is associated with the prognosis of other kinds of carcinoma, including prostate cancer, esophageal carcinoma, gingival squamous cell carcinoma and colorectal carcinomas." (PMID 22536440, 2012). "Furthermore, USP11 is functionally implicated in the resistance to 5-fluorouracil in colorectal cancer through activating autophagy by stabilizing valosin-containing protein (VCP)." (PMID 41419456, 2025). "Recently, high expression levels of VCP/p97 were found to be involved in colorectal cancer growth, invasion and metastasis through STAT3 signaling activation." (PMID 35158912, 2022). "Although the authors excluded the contribution of VCP to the anti-inflammatory effects of azithromycin, it should be noted that VCP over-expression induces STAT3 phosphorylation in colorectal cancer cell lines." (PMID 31849581, 2019). "Elevated expression of VCP is observed in certain types of cancer tissues, e.g., colorectal carcinomas, pancreatic endocrine neoplasms, follicular thyroid cancer, hepatocellular and lung carcinoma." (PMID 24392146, 2014). "Studies have shown that the expression levels of VCP correlate with the prognosis and recurrence of specific human cancers, including hepatocellular, gastric and colorectal carcinomas." (PMID 25009651, 2014). "VCP is overexpressed in many solid tumors, including prostate and pancreatic cancers, esophageal and colorectal carcinomas, osteosarcoma." (PMID 22216170, 2011). "The VCP expression level is an independent prognosticator for recurrence of colorectal carcinoma and patient survival." (PMID 18205950, 2008). "A significant correlation between high VCP/p97 expression and advanced T-stage has been demonstrated for gingival squamous cell carcinomas, gastric carcinomas, follicular thyroid carcinomas, and colorectal carcinomas." (PMID 41357812, 2025). "Interestingly, VCP promotes the growth, invasion, and metastasis of colorectal cancer through activation of STAT3 signaling." (PMID 35841038, 2022). "In conclusion, these findings confirm that USP11 could promote colorectal cancer cells resistance to 5-Fu through inducing autophagy dependent on VCP." (PMID 33758608, 2021). "In the present study, we demonstrated that USP11 could induce resistance to 5-Fu in colorectal cancer both in vitro and in vivo via activation of autophagy through stabilizing VCP." (PMID 33758608, 2021). "Furthermore, a high correlation between elevated expression of VCP and progression, prognosis, and metastatic potential in pancreatic, hepatic, esophageal, prostate, and colorectal cancers has previously been reported." (PMID 26934314, 2016). "Additionally, clinical studies have identified a correlation between elevated VCP expression and the progression, prognosis, and metastatic potential of esophageal carcinoma, colorectal carcinoma, and prostate cancer." (PMID 22216170, 2011). "Interestingly, VCP, a partner of derlin-1 in the retrotranslocation complex, was overexpressed in colorectal carcinomas." (PMID 18205950, 2008). "Furthermore, VCP/p97 is discussed to be involved in certain types of human tumors such as hepatocellular and colorectal carcinomas as well as breast cancer." (PMID 18279508, 2008). "Additionally, clinical studies have identified a correlation between elevated VCP expression and the progression, prognosis, and metastatic potential of esophageal carcinoma, colorectal carcinoma, prostate cancer, non-small cell lung carcinoma, and pancreatic cancer." (PMID 34917511, 2021). "In another study, VCP knockdown was demonstrated to inhibit invasion, chemoresistance, and cell proliferation, and stimulate apoptosis in HCT116 CRC (colorectal cancer) cells." (PMID 39473740, 2024).
colorectal cancer (continued). "If this were to apply generally to other colorectal cancer lines, this would indicate the potential of UBR5 and VCP/p97 as new enzymatic targets for therapeutic intervention in colorectal and other β-catenin-dependent cancers." (PMID 28689657, 2017). "Valosin-containing protein (VCP) was previously shown to exhibit high expression in colorectal cancer (CRC) tissues as compared with that in normal tissues; however, the role of VCP in human CRC cells has remained to be elucidated." (PMID 27344168, 2016). "This might be expected, given our results from the colorectal cancer cell line HCT116 whose β-catenin-dependent transcription is attenuated by UBR5 KO and whose proliferation is slowed down by VCP/p97 inhibition." (PMID 28689657, 2017). "VCP was significantly more enriched at these loci in FU-UR-1 and ASPS-1 cells than in control HCT116 and ASKA cells (colorectal carcinoma, synovial sarcoma cell lines, respectively, lacking AT3)." (PMID 38326311, 2024).
pancreatic cancer (17 papers, 2009 to 2024). "Specifically, they identified some differentially expressed LD-associated genes in patients with pancreatic cancer, including VCP." (PMID 34576340, 2021). "VCP is overexpressed in many solid tumors, including prostate and pancreatic cancers, esophageal carcinomas, and osteosarcoma." (PMID 27344168, 2016). "More recently, global genomic analysis of pancreatic cancer has confirmed VCP overexpression by Serial analysis of gene expression (SAGE)." (PMID 22216170, 2011). "In this study, we examine whether miR-198-mediated downregulation of VCP may contribute to autophagy disruption and identify a potential mechanism through which miR-198 administration can sensitize pancreatic cancer cells to gemcitabine treatment." (PMID 37631252, 2023). "Hence, the increase in miR-198 levels in pancreatic cancer cells induces a decrease in tumor growth and metastasis and an increase in patient survival by directly targeting VCP and other factors." (PMID 34576340, 2021). "In addition to the prognostic and therapeutic molecular studies, it is important to determine the presence and function of it has been proven to exist in two different tumors (glioma and prostate cancer) SVIP and its interacting protein p97/VCP in pancreatic cancer types." (PMID 39473740, 2024). "In view of the potential function of the p97/VCP and SVIP genes in pancreatic cancer progression, the next step was to perform functional analyses." (PMID 39473740, 2024). "Immunocytochemistry and immunofluorescence were performed to detect the cellular localization and presence of p97/VCP and SVIP in pancreatic cancer cells." (PMID 39473740, 2024). "For this reason, we aimed to examine the expression of SVIP and p97/VCP on two ERAD pathway proteins and their efficacy on pancreatic cancer migration and invasion." (PMID 39473740, 2024). "It was found that miR-198 transcription is reduced in pancreatic cancer and that miR-198 inhibition increases PBX-1 and VCP expression; dysregulation of the PBX-1/VCP axis enhances tumorigenicity." (PMID 39129784, 2024). "p97/VCP was identified in the nucleus and cytoplasm of MIA PaCa-2 and PANC-1 pancreatic cancer cells." (PMID 39473740, 2024). "Overexpression of miR‐198 in pancreatic cancer cells inhibited tumour growth, metastasis, and promoted survival by directly targeting PBX‐1, MSLN, and VCP." (PMID 35068042, 2022). "In pancreatic cancer, reconstitution of miR-198 resulted in reduced tumor growth and metastasis through direct targeting MSLN, PBX-1, and VCP." (PMID 26852230, 2016). "The probable location of p97/VCP and SVIP in pancreatic cancer cell lines is currently unknown." (PMID 39473740, 2024). "Pancreatic cancer cells were transiently transfected with SVIP siRNA (SVIPsi), p97/VCP siRNA (p97/VCPsi), and the control siRNA (Csi) to detect whether the protein expressions of SVIP and p97/VCP were influenced by these suppressions." (PMID 39473740, 2024). "Other antigens such as EF-Tu, HSP70, HSP60, aldolase, fumarate hydratase, aldose reductase, aconitase, HnRNP1, EF-TU, VCP and enolase have been reported for other cancers including cutaneous T cell lymphoma, and renal, hepatic, lung and pancreatic cancers but not for melanoma." (PMID 19381273, 2009).
Alzheimer disease (15 papers, 2010 to 2025). A progressive, neurodegenerative disease characterized by loss of function and death of nerve cells in several areas of the brain leading to loss of cognitive function such as memory and language. "Aside from causing neurodegeneration, VCP variants also modulate the pathologies of Alzheimer’s disease (AD) and some polyglutamine (polyQ) diseases, such as Huntington’s disease (HD) and spinocerebellar ataxia type 3 (SCA3/Machado-Joseph disease)." (PMID 37545006, 2023). "To test the effects of VCP inhibitors on a physiological tau seed source, we tested tauopathy brain lysates from AD (Alzheimer’s disease) and CBD (corticobasal degeneration) patients." (PMID 38826306, 2024). "Interestingly, VCP expression is described as a biomarker of Alzheimer's disease which is also an age-related disease." (PMID 21085581, 2010).
osteosarcoma (15 papers, 2011 to 2025). A usually aggressive malignant bone-forming mesenchymal neoplasm, predominantly affecting adolescents and young adults. "VCP also correlates with increasing recurrence and poor prognosis in patients with various cancers, and very recent studies have shown that its inhibition in osteosarcoma results in loss of malignancy and decreased metastasis." (PMID 27259278, 2016). "In a study using p97/VCP siRNAs in human osteosarcoma cell lines, it was determined that migration rate and invaded cell count both decreased in cells where VCP was downregulated, compared with those transfected with Neg-LV after 24 h of transfection." (PMID 39473740, 2024). "For instance, VCP expression declines in osteosarcoma cell lines, however, VCP expression is continuously increased in its subline LM8 cells, which display higher metastatic potential." (PMID 32481679, 2020). "Murine osteosarcoma cells transfected with the VCP gene exhibited constant activation of NF-кB, rapid degradation of phosphorylated-inhibitor кBα, decreased apoptosis rates after tumor necrosis factor α stimulation, and increased metastatic potential." (PMID 27344168, 2016). "VCP has been shown to regulate NFκB signaling, which is critical for the metastasis of osteosarcoma cell line." (PMID 22216170, 2011). "The study on osteosarcoma also indicates the UPS function of VCP as a regulator of NFκB mediated tumor metastasis." (PMID 22216170, 2011). "Additionally, VCP has been implicated in promoting EMT through the TGF-β1/Smad2/3 signaling pathway, while its inhibition attenuates osteosarcoma cell invasion and metastasis." (PMID 39802400, 2025). "RT-qPCR showed that AT3:VCP targets were more highly expressed in mouse AT3-initiated tumors treated with vehicle than in control mouse tumors (osteosarcoma, synovial sarcoma); CB-5083 for 4 days immediately prior to harvest also reduced expression of most of these." (PMID 38326311, 2024). "VCP has also been strongly involved in cancer, with over-activity of VCP found in several cancers such as prostate, pancreatic, endometrial, esophageal cancers and osteosarcoma." (PMID 35841038, 2022). "Moreover, the authors of a recent study modulated VCP/p97 expression and observed a connection with autophagy induction, anoikis resistance and osteosarcoma cell metastasis." (PMID 34576340, 2021). "Additionally, USP2, recruited by VCP, enhances the stability of fatty acid synthase (FASN) by removing K48−linked ubiquitin chains, a process whose inhibition reverses pro-tumorigenic effects in osteosarcoma cells." (PMID 40370434, 2025). "Thus, approaches targeting the VCP/miR-129-5p signaling pathway might represent a therapeutic strategy for osteosarcoma management." (PMID 34576340, 2021). "The expression of miR-129-5p in osteosarcoma cells is lower than that in normal tissues and cells, and the increase of miR-129-5p may be mediated by demethylation and inhibit the migration and invasion of OS cells by targeting VCP in OS." (PMID 32953888, 2020). "VCP/p97 is downregulated in liver-bone-kidney alkaline phosphatase (L/B/K ALP) and CD99 glycoprotein-transfected osteosarcoma cells, which show a low metastatic ability, and this observation correlates with decreased NF-κB activity." (PMID 34576340, 2021). "AURKB is a serine/threonine kinase that has been proposed to stimulate the invasion and proliferation of osteosarcoma through PTK2/PI3K/AKt/NF-κB signaling pathway and VCP." (PMID 33858425, 2021).
viral infection (14 papers, 2016 to 2025). "Considering its pivotal role in viral replication, VCP emerges as a highly promising target for the development of antiviral therapeutics, with broad implications for treating a variety of viral infections." (PMID 41288382, 2025). "One protein that has been extensively studied in the context of viral infections due to its ubiquitous presence in cells and involvement in many cellular processes is valosin-containing protein (VCP)." (PMID 39519185, 2024). "Considering the numerous functions performed in the cell and the widespread occurrence of VCP, the involvement of this protein during viral infections has begun to be studied." (PMID 39519185, 2024). "VCP plays a role in the viral infection cycle at various stages, including receptor binding and entry, replication, and viral egress." (PMID 39519185, 2024). "As the effect of VCP/p97 inhibition on the replication of both RSV and VSV was similar when added prior to infection or after completion of the entry process, VCP/p97 likely acts downstream of these early steps in the viral infection cycle." (PMID 35615506, 2022). "The CTL response to all analyzed epitopes was significantly reduced upon CB-5083 treatment, which reflects the inability of the mice to cope with the viral infection in presence of the VCP/p97 inhibitor." (PMID 36456548, 2022). "Previous studies have described UBR5 function in regulatory pathways and cancer but not much is known about how it functions in tandem with TER94/VCP during viral infections." (PMID 33986255, 2021). "Besides its multifaceted role in regulating cellular homeostasis, the VCP/p97 ATPase serves as an important host factor in viral infections." (PMID 34578461, 2021). "In that context, VCP knockdown also significantly reduced viral infection." (PMID 31636613, 2019). "Given the functionally pleotropic nature of VCP, it is unsurprising that knockdown results in multifactorial effects on the virus and potentially reflects the diverse roles of ubiquitin modulation and signaling during virus infection." (PMID 28494016, 2017). "VCP might also function as a counterpart for the stress response in these viral infections." (PMID 35063505, 2022). "Indeed, VCP/p97 has been demonstrated to participate in numerous stages of viral infection." (PMID 36456548, 2022). "Furthermore, we could not exclude the possibility that VCP is involved in the entry steps of viral infection." (PMID 35063505, 2022).